CD4 (CD4 molecule)
Diseases named in the same sentence as CD4 in open-access papers (continued):
Sharing a sentence is not in itself a finding about the gene and the disease.
malaria (continued). "While these studies suggest the involvement of IL-10 and TGFβ in CD4+CD25+ Treg induction during malaria, no causal connection has been proven to date." (PMID 19680449, 2009). "IL-10 is a crucial immunoregulatory cytokine in both human and murine malaria; we have recently identified CD4+ T effector cells as a major source of IL-10, but the source of IL-10 in human malaria infection is unknown." (PMID 19343213, 2009). "To test whether TGFβ plays a role in the induction of Foxp3+ CD4 T cells by malaria-infected RBCs, we added TGFβ-neutralizing antibody to the iRBC∶PBMC co-culture." (PMID 19680449, 2009). "Throughout all the analyses the phenotypes consistently associated with subsequent malaria incidence were cultured TRAP response, and the CD4+CD25high population, but there was also weaker evidence of some association with the CD56dim population and reduced incidence." (PMID 18446217, 2008). "We found that cultured responses to TRAP but not CS were significantly associated with reduced malaria, whilst increased numbers of CD4+ CD25high T cells were associated with increased malaria." (PMID 18446217, 2008). "Using a mouse malaria model, the interactions of DCs and naïve CD4+ T cells have been analysed." (PMID 18495039, 2008). "CD4 cell count has previously been associated with an increased risk of malaria infection, and a causal relationship between HIV-related immunosuppression and malaria-related mortality would be strengthened by observing an effect between lower CD4 count and increased mortality." (PMID 17973997, 2007). "Since much of the pathogenesis of acute blood stage malaria in this model has been ascribed to pro-inflammatory responses induced in part by IFN-γ from Th1 CD4 + T cells, it will also be important to determine the extent of the pathological sequelae in mosquito-transmitted infections." (PMID 17555592, 2007). "With 15 percent of 817,255 HIV infected persons with CD4 counts less than 200/μL and assuming the rest have CD4 counts greater than 400/μL, the number of malaria episodes would be 2,222,934 for those will low CD4 counts and 661,975 for those with CD4 counts of >400/μL." (PMID 18093319, 2007). "In other studies of experimental malaria, IL-27 appears to be an important cytokine for the development of protective immunity and may be essential for the development of IL-10-producing regulatory CD4 T-cells." (PMID 40972121, 2025). "After establishing that CXCR6+ CD127− Tr1 cell were the predominant CD4+ T cell population responding to malaria in children, we leveraged the longitudinal, paired nature of the MUSICAL clinical study to determine whether these cells correlated with clinical outcomes of infection." (PMID 41000872, 2025). "Responses were notably more frequent among those sampled at 2–12 weeks post-infection (82.6%) than in those sampled within 2 weeks of their last malaria episode (36.4%), indicating that it may take weeks for newly primed CD4+ T cells to enter the peripheral circulation." (PMID 39993000, 2025). "Thus, protective immunity to malaria relies on a balanced response by effector CD4+ T cells." (PMID 40132035, 2025). "Furthermore, a key objective of this study was to determine whether significant differences exist between the control group and the malaria patients about their levels of CD4+, CD3+, CD8+, and CD45+ lymphoid cells." (PMID 38987710, 2024). "However, CD4+ T cell polarization, germinal center formation, and antibody production were profoundly altered, a finding that has implications for vaccination schemes in malaria-endemic regions." (PMID 36715223, 2023). "Thus, given the key immune regulatory roles for type I IFNs previously reported in malaria and, in particular, their role in promoting the transition of Th1 cells to Tr1 cells, we examined the role of CD4+ T cell STING on the development and activation of Tr1 cells." (PMID 37781920, 2023).
malaria (continued). "Furthermore, understanding factors that limit Tr1 induction—and promote CD4+ T cell production of TNFα—may help in the rational design of effective vaccines in malaria-endemic settings." (PMID 37634385, 2023). "Importantly, we reveal in malaria-infected participants the existence of a population of clonally expanded memory CD4+ T cells that share identical TCR clonotypes and express a robust cytolytic signature and the ZEB2 master regulator of terminally differentiated effector cells." (PMID 38001069, 2023). "Some studies have found that P. falciparum-infected RBCs (iRBCs) or parasite products can render human DCs refractory to activation and restrict priming of CD4+ T cells in vitro, and humans with malaria have fewer and less activated circulating DCs than healthy controls." (PMID 36715223, 2023). "Also a decreased risk of clinical malaria once infected has been associated with the frequency of CD4 T cells producing IL-10 but not inflammatory cytokine like IFN-γ." (PMID 36787308, 2023). "It is also unknown whether CD4+ T cell type I IFN production plays any role in the development of antiparasitic immune responses during malaria, and if so, the identity of relevant cellular and molecular pathways that mediate type I IFN-dependent Tr1 cell development." (PMID 37781920, 2023). "Pre-existing malaria infection promotes SIV replication, which may lead to faster progress in SIV disease in coinfected animals, while subsequent malaria enhances the CD4+ TCM response and virus-specific T cell immunity, resulting in the improved survival of SIV-infected hosts." (PMID 35778766, 2022). "Children repeatedly exposed to malaria in endemic settings develop a substantial proportion of antigen-specific IL-10+IFN-γ+ CD4+ T cells, prompting the question whether Tr1-mediated tolerance may contribute to the development of clinical immunity to Plasmodium infections." (PMID 36389662, 2022). "The positive correlation between CD4 counts with RBC, Hgb and HCT among MHC could be explained most likely by the fact that decreased CD4 count as HIV disease progresses could cause anemia by myelosuppression from HIV that impairs erythropoietin, malaria may also induce removal of parasitized RBC." (PMID 35245289, 2022). "Thus, we consider that enhanced cellular and humoral adaptive immunity might contribute to rapid clearance of malaria among adults, likely in a PD-1-dependent manner due to induction of CD4+ T cells exhaustion in P. yoelii 17XNL infected 8-week-old mice." (PMID 33430765, 2021). "At the opposite of the interactions spectrum, recurrent or prolonged malaria episodes may activate latently infected resting CD4+ T-cells, inducing latent virus reactivation and potentially reducing the reservoir burden in patients on effective combination antiretroviral therapy (cART)." (PMID 34442727, 2021). "Several studies demonstrated that CTX maintenance treatment, regardless of CD4 count, in malaria highly endemic countries was associated with a significant reduction in malaria and other bacterial infections incidence, related hospitalisations, and parasitemia burden." (PMID 34442727, 2021). "The contribution of CD4+ Th2 cells remains unknown in anti-malaria immunity." (PMID 33363057, 2020). "Thus, we propose a model in which inhibition of LAG-3 on parasite-specific CD4+ T cells unleashes their ability to produce effector cytokines, altogether contributing to achieve superior levels of protection in malaria-infected hosts, independent from parasite-specific humoral responses." (PMID 33519801, 2020). "Whether the CD38‐expressing CD4+ T cells associated with treatment failure in clinical malaria in Uganda had increased expression of CD4 was not reported." (PMID 33282291, 2020). "However, whether a detectable clonal malaria-specific CD4+ T cell response that is conserved between individuals, and thus a potential focal target for therapeutics, is induced, has not previously been demonstrated." (PMID 33329568, 2020).
malaria (continued). "However, the function and characteristics of CD38‐expressing CD4+ T cells in individuals naturally exposed to malaria, and during an acute malarial infection, are unknown." (PMID 33282291, 2020). "We also note that a low CD4 count (<250 cell/mm3) was associated with a fourfold increase in risk of having malaria parasites independent of whether CTX was discontinued." (PMID 33175844, 2020). "Compared to those with asymptomatic infections and the uninfected group, children with symptomatic malaria demonstrated a significant reduction in the proportions and absolute numbers of peripheral blood total T cells, CD4 + and CD8 + T cells, and CD19 + B cells (p < 0.0001 for all comparisons)." (PMID 33036624, 2020). "Moreover, NK cell cross-talk with dendritic cells is important for CD4 T cell priming in murine malaria models, suggesting that NK cells may bias TH1 polarization through multiple pathways." (PMID 31156642, 2019). "In addition, SIV infection alters the humoral immune response, the homeostasis of CD4+ T cells and immune activation during the acute phase of Pc malaria, which may lead to impaired immunity and exacerbated malaria." (PMID 31718574, 2019). "Similarly, malaria has been reported to reduce the CD4 and CD8 counts and the CD4:CD8 ratio." (PMID 31428162, 2019). "Moreover, the qualitative and quantitative effects of a malaria/HIV/DR-TB triple infection on the CD4 cells are unknown." (PMID 31428162, 2019). "Consistent with previous research on blood-stage malaria, our data suggest that involvement of neddylation in CD4+ T survival does not appear to be linked to Fas-mediated mechanism, but rather correlates with the mitochondria associated process, with Bcl-2 being the major molecule to be regulated." (PMID 30462731, 2018). "However, the function of IL-10 in malaria is still unclear as IL-10 producing CD4+ T cells were involved in dampening severe pathology during Plasmodium infection whereas, it had also been reported to reduce levels of IFN-γ and TNF-α, which helps the parasites to escape the immune response." (PMID 28830553, 2017). "However, evidence from a Zambian study seems to have provided useful suggestion that interpretation of absolute CD4 count in HIV infected might be biased during or just after a clinical malaria episode." (PMID 28346490, 2017). "However, in human, there is only one published report in malaria caused by P. falciparum, demonstrating that circulating PD-1+CXCR5+CD4+ T cells from patients have characteristics of GC Tfh cells, and our study represents the first report of an increase in Tfh cells following P. vivax infection." (PMID 28700710, 2017). "Thus, we assessed whether type I IFNs also impact Blimp-1 expression in CD4 T cells during experimental malaria or chronic LCMV infection." (PMID 27732671, 2016). "P. falciparum CSP T cell regions contain highly polymorphic CD4+ and CD8+ T cell epitopes, and only two variants bind HLA-B35; naturally induced CD8+ T cells to these two variants are not cross-reactive, suggesting the influence of local HLA on malaria antigenic variation." (PMID 27695088, 2016). "In brief they showed that among HIV-infected adults on ART with a CD4 count above 250 cells/mm3, discontinuing CTX significantly increased the risk of CTX preventable bacterial infections (particularly pneumonia), and of malaria and led to an increase in hospital admission rates." (PMID 27536738, 2016). "However, it is unclear whether the risk of malaria continues to decrease after the immune system has sufficiently recovered on ART, or whether there is a CD4 threshold after which malaria incidence stabilizes." (PMID 27417903, 2016). "However, since red blood cells lack MHC-II molecules, so the mechanism by which CD38+ CD4+ T cells could exert their cytotoxic function in blood-stage malaria remains to be elucidated." (PMID 27662621, 2016).
malaria (continued). "Consequently, it is probable that IL-10–producing CD4+ T cells may only be effectively maintained in the presence of malaria Ag in context of TCR engagement." (PMID 27630165, 2016). "Together, these data suggest that in utero malaria exposure early in pregnancy may drive a regulatory response, while late exposure to parasites present at the time of delivery may drive an activated effector CD4 T cell response." (PMID 27717402, 2016). "Moreover, significantly fewer infection-induced CD4+YFP+GFP+ T cell–derived cells were obtained following adoptive transfer into malaria-infected and drug-cured recipient mice in comparison with total Ag-experienced CD4+ T cells or CD4+YFP+GFP− counterpart cells." (PMID 27630165, 2016). "We evaluated the CD4+ T cell response in patients with acute imported malaria in Hamburg, Germany to investigate whether the induction of coinhibitory receptors downregulates the T cell response in acute P. falciparum malaria and to further elucidate involved regulatory pathways." (PMID 27802341, 2016). "Depletion of CD4+CD25+ T cells (putative Tregs) has been shown to abrogate malaria specific T-cell cytokine production, suggesting that Tregs play a functionally suppressive role in malaria-exposed infants, regardless of whether they are increased in frequency." (PMID 27717402, 2016). "Similarly, a high percentage of adults and lesser numbers of children living in malaria endemic areas possess antibodies specific for CS C-terminal sequences that represent CD4+ and CD8+ recognition sites for human and murine T cells (i.e., UTC, TH3.R and CS.T3 regions)." (PMID 25933001, 2015). "Flow cytometric analysis of non-CD4 T cells and monocytes demonstrated a significant increase in the percentage of cells in early apoptosis (Annexin V+) in P. vivax-infected donors (2.03% and 1.93%, respectively) compared to malaria-naive donors (0.99% and 0.14%, respectively) (p < 0.0001 for both)." (PMID 25559491, 2015). "However, due to the relatively small number of animals in the present study, we did not observe a significant effect of malaria on CD4+ TCM cell apoptosis, but monkeys that were co-infected with malaria did maintain a relatively higher level of apoptotic CD4+ TCM cells." (PMID 25487036, 2014). "Moreover, the effect of malaria on CD4+ TEM cell apoptosis was significant." (PMID 25487036, 2014). "The in vitro study also demonstrated that Pf extract could activate the memory CD4+ T cells, along with the production of virion, and could induce the apoptosis of these cells, suggesting that malaria-induced reservoir purging was partly related to the Plasmodium itself." (PMID 25487036, 2014). "However, children responding to a homologous cys2 DBLα-tag induced IL-10–secreting CD4+ T cells during acute disease but IFN-γ–secreting CD4+ T cells 16 wk after an acute malaria episode, suggesting that a stable population of effector memory Th1 cells was maintained." (PMID 24453249, 2014). "Frequencies of IFNγ/IL10 co-producing CD4+ T cells, which express the Th1 transcription factor T-bet, were significantly higher in children with ≥2 prior episodes/year compared to children with <2 episodes/year (P<0.001) and inversely correlated with duration since malaria (Rho = −0.39, P<0.001)." (PMID 24415936, 2014). "However, when assessed in a multivariate model, the frequency of malaria-specific IFNγ/IL-10 co-producing CD4+ T cells remained strongly associated with the duration since malaria, whereas the total prior incidence was no longer significant." (PMID 24415936, 2014). "The “control” population we used to assess temporal changes in malaria had higher CD4 cell counts than our study population, and, therefore, changes in disease incidence in these women may not be a true representation of changes in disease incidence in our study population." (PMID 24363547, 2013).
malaria (continued). "Finally, endemic exposure to malaria in rural Kenya may have influenced the expansion of few discrete CD4 T cell populations with specific functional signatures." (PMID 23383106, 2013). "Thus, analyzing the effects of JES6-1 treatment on P. chabaudi malaria contributes to the efforts to understand the molecular mechanisms responsible for activation and regulation of the CD4+ T cell response to Plasmodium aiming to ameliorate the outcome of the disease." (PMID 22272258, 2012). "We were interested in whether there are differences in the type, magnitude or duration of CD4+ T-cell responses to PfEMP1 dominantly expressed at the time of acute disease in children suffering from severe malaria or infected with parasites expressing specific subgroups of PfEMP1." (PMID 22272280, 2012). "The induction of CD4+ T cells against common epitopes could be relevant to the issue of AMA1 polymorphism if these epitopes are important for protection, as indicated by studies of AMA1 in the P. chabaudi rodent malaria model." (PMID 21698193, 2011). "It has been proposed that antigenic diversity, inhibition of maturation of dendritic cells, and apoptotic deletion of malaria-specific T cells impair the development of memory responses after malaria infection, in particular impeding the development and/or longevity of memory CD4+ T cells." (PMID 21347351, 2011). "The information provided here is fundamental for unravelling the molecular mechanisms behind the early phase of the CD4+ T cell response to Plasmodium infection, knowledge that could help explain why people develop severe malaria and how they get immune against the symptoms of the disease." (PMID 21814579, 2011). "To investigate whether anti-IP-10 treatment had an effect on T cell activation during malaria, we first examined the percentage of activated CD4+ and CD8+ T cells expressing CD69 and CD25 in anti-IP-10 and isotype-control-treated mice after P. berghei ANKA infection." (PMID 19343215, 2009). "Using a co-culture system of malaria-infected red blood cells (iRBCs) and peripheral blood mononuclear cells from healthy individuals, we found that two populations of Foxp3hi and Foxp3int CD4+CD25hi T cells with a typical Treg phenotype (CTLA-4+, CD127low, CD39+, ICOS+, TNFRII+) were induced." (PMID 19680449, 2009). "Chronic infection with malaria parasites has been associated with immunosuppressive responses to the parasite and to unrelated antigens.In animal models of malaria, the release of interferon gamma (IFN-γ) has been shown to mediate protection when secreted by Plasmodium specific CD8 or CD4 T-cells." (PMID 20037644, 2009). "Since uncomplicated malaria has previously been reported to alter lymphocyte subpopulations, we compared the percentage frequency of total CD3+, CD4+, and CD8+ T-cell subsets in our study groups." (PMID 41285032, 2025). "Future studies should address the potential of the antigens reported here to elicit liver-resident CD4+ and CD8+ cellular immunity and their capacity to establish protection against malaria." (PMID 40487438, 2025). "Consistent with earlier studies, we observed significant changes in the percentage frequencies of CD4+ and CD8+ T-cell subsets in children with an episode of uncomplicated malaria compared to community controls." (PMID 41285032, 2025). "“Hybrid Th1/Tfh” or “Th1-like Tfh” have been used to describe any IFN-γ+ CD4 T cell also expressing IL-21 and/or CXCR5, functional markers of Tfh in Malaria models." (PMID 40356908, 2025). "This process is essential for the subsequent adaptive immune response, including the activation of CD4+ and CD8+ T cells that contribute to the defense against malaria." (PMID 39861032, 2025). "Children with uncomplicated malaria and 4-week recovery had elevated levels of TEMRA CD4+CD45RA+CCR7− versus community controls (1.8% vs 0.7% and 1.6% vs 0.7%, respectively)." (PMID 41285032, 2025).